SMIM10L2B (small integral membrane protein 10 like 2B)
Synonyms: LINC00087; NCRNA00087; RP11-85L21.2
Tractability: No criterion of Open Targets' tractability assessment is met for any kind of drug.
Gene: Protein-coding gene on chromosome X (135,094,985 to 135,098,712, reverse strand). Ensembl gene ENSG00000196972.
Homologues: Orthologues: chimpanzee SMIM10L2B (100% identical), dog SMIM10L2A (97% identical), mouse Smim10l2a (91% identical), zebrafish smim10l3 (51% identical). Paralogues in human: SMIM10L2A (100% identical), SMIM10L3 (76% identical), SMIM10 (71% identical), SMIM10L1 (60% identical).